RPS12 (ribosomal protein S12)
Description:
Part of the small subunit (SSU) processome, first precursor of the small eukaryotic ribosomal subunit. During the assembly of the SSU processome in the nucleolus, many ribosome biogenesis factors, an RNA chaperone and ribosomal proteins associate with the nascent pre-rRNA and work in concert to generate RNA folding, modifications, rearrangements and cleavage as well as targeted degradation of pre-ribosomal RNA by the RNA exosome. Subunit of the 40S ribosomal complex (By similarity).
Synonyms: S12; eS12
Tractability: Small molecule: an approved drug acts on it; a structure with a bound ligand is known; a high-quality ligand is known. PROTAC: ubiquitination databases record sites on it; its protein half-life has been measured; a small molecule that binds it is known. Other modalities: a drug acting on it is in phase 2 or 3 trials.
Target class: Other cytosolic protein
Gene: Protein-coding gene on chromosome 6 (132,814,557 to 132,817,577, forward strand). Ensembl gene ENSG00000112306.
Subcellular location: Cytoplasm; Nucleus, nucleolus
Subcellular location (Human Protein Atlas): Cytosol; Golgi apparatus; Vesicles
Pathways (Reactome):
Metabolism of proteins: Eukaryotic Translation Termination; Formation of a pool of free 40S subunits; Formation of the ternary complex, and subsequently, the 43S complex; GTP hydrolysis and joining of the 60S ribosomal subunit; L13a-mediated translational silencing of Ceruloplasmin expression; PELO:HBS1L and ABCE1 dissociate a ribosome on a non-stop mRNA; Peptide chain elongation; Ribosomal scanning and start codon recognition; SRP-dependent cotranslational protein targeting to membrane; Translation initiation complex formation; ZNF598 and the Ribosome-associated Quality Trigger (RQT) complex dissociate a ribosome stalled on a no-go mRNA
Disease: SARS-CoV-1 modulates host translation machinery; SARS-CoV-2 modulates host translation machinery; Viral mRNA Translation
Metabolism of RNA: Major pathway of rRNA processing in the nucleolus and cytosol; Nonsense Mediated Decay (NMD) enhanced by the Exon Junction Complex (EJC); Nonsense Mediated Decay (NMD) independent of the Exon Junction Complex (EJC)
Cellular responses to stimuli: Response of EIF2AK4 (GCN2) to amino acid deficiency
Developmental Biology: Regulation of expression of SLITs and ROBOs
Metabolism: Selenocysteine synthesis
Gene Ontology:
Molecular function: protein binding; RNA binding; structural constituent of ribosome
Biological process: positive regulation of canonical Wnt signaling pathway; ribosomal small subunit biogenesis; cytoplasmic translation; maintenance of translational fidelity; translation
Cellular component: cytoplasm; cytosol; cytosolic ribosome; cytosolic small ribosomal subunit; membrane; small-subunit processome; nucleoplasm; nucleolus; ribosome
Genetic constraint (gnomAD): Loss-of-function variants: 0 observed, 8.21 expected, observed/expected ratio (o/e) 0, 90% interval 0 to 0.36. That is too few expected variants to judge how well the gene tolerates losing a copy. Missense variants: 123 observed, 132.43 expected, observed/expected ratio (o/e) 0.93, 90% interval 0.8 to 1.08. Synonymous variants: 61 observed, 48.79 expected, observed/expected ratio (o/e) 1.25, 90% interval 1.02 to 1.55.
Homologues: Orthologues: chimpanzee RPS12 (100% identical), dog RPS12 (100% identical), guinea pig RPS12 (100% identical), pig RPS12 (100% identical), rabbit RPS12 (100% identical), rat Rps12l2 (98% identical), tropical clawed frog rps12 (98% identical), zebrafish rps12 (97% identical), Drosophila melanogaster RpS12 (63% identical), Caenorhabditis elegans rps-12 (59% identical).
Diseases named in the same sentence as RPS12 in open-access papers:
RPS12 is named in the same sentence as 31 diseases in open-access papers, as found by Europe PMC text mining. Sharing a sentence is not in itself a finding about the gene and the disease. The quoted sentences say what the papers report.
diffuse large B-cell lymphoma (5 papers, 2008 to 2024). "Studies have shown that RPS12 gene deletion is associated with diffuse large B-cell lymphoma." (PMID 34350180, 2021). "How mammalian RpS12 might be involved in Diambond Blackfan Anemia or cancer has not been described, although a possible association has been reported between RpS12 deletion and Diffuse Large B Cell Lymphoma." (PMID 31841522, 2019). "Deletions of RPS12 are frequently observed in diffuse large B cell lymphomas, and eS12 has been reported to play a role as a stimulator of WNT secretion in cancer cells, which is particularly important in the context of triple-negative breast cancer initiation and progression." (PMID 39062596, 2024). "In mammals, it has been reported that Rps12 deletions are frequent in diffuse large B cell lymphoma samples, and that Rps12 distribution in the ribosomes is altered under hypoxic conditions in the human embryonic kidney cell line, HEK293, resulting in changes of their translatome." (PMID 37272618, 2023). "RPS12, Secernin, CDC10 were found to be upregulated in human colorectal tumors, gastric cancers, diffuse large B-cell lymphomas, respectively." (PMID 18442364, 2008).
gastric cancer (4 papers, 2008 to 2025). A primary or metastatic malignant neoplasm involving the stomach. "Key findings include the identification of EIF1 and RPS12 as critical genes with causal links to gastric cancer progression, significantly influencing immune infiltration and key signaling pathways such as oxidative phosphorylation and ribosome biogenesis." (PMID 41261408, 2025). "The RPS12 gene has been demonstrated to be a hypoxia-related gene, and high expression of the RPS12 gene increases the risk of gastric cancer, squamous cell carcinoma and HCC." (PMID 34350180, 2021). "RPS12 gene closely associates with gastric cancer cell-proliferation and migration and the inhibition of RPS12 expression using RNAi has been found to reduce S100A4 expression and decrease S100A4 promoter activity in gastric cancer cells." (PMID 29069865, 2017).
breast carcinoma (3 papers, 2017 to 2020). "As Wnt signaling is particularly important in the context of breast cancer initiation and progression, RPS12 might be implicated in tumorigenesis in this and other Wnt-dependent cancers." (PMID 33273532, 2020).
colorectal cancer (3 papers, 2020 to 2022). A primary or metastatic malignant neoplasm that affects the colon or rectum. "For example, the expression of RPL5, RPS3, RPS6, RPS8, and RPS12 in colorectal cancer was higher than that in normal colorectal mucosa." (PMID 33584809, 2020). "Increased expression of ribosomal protein genes including rpS3, rpS6, rpS8, rpS12 and rpL5 has been reported in colorectal cancer." (PMID 32973493, 2020). "In colorectal cancer, the elevation of some specific small RPs, including RPS3, RPS6, RPS8, and RPS12, increases ribosome biogenesis and possibly leads to the activation of extra-ribosomal functions such as DNA replication, RNA splicing and modification, and cell growth." (PMID 35159381, 2022).
cervical cancer (2 papers, 2002 to 2022). A primary or metastatic malignant neoplasm involving the cervix. "The next obvious objective is to evaluate the possible role of the ribosomal protein S12 gene in pre-invasive cervical cancer." (PMID 11870519, 2002).
glioma (2 papers, 2019 to 2024). A benign or malignant brain and spinal cord tumor that arises from glial cells (astrocytes, oligodendrocytes, ependymal cells). "The higher expression of BMP2, RPL18A, RPL19, and RPS12 is associated with better outcomes in patients with glioma." (PMID 38672212, 2024). "In our study, the overexpression of RPs, such as RPSA, RPL18A, RPL19, and RPS12, was associated with a better prognosis in patients with glioma." (PMID 38672212, 2024). "Of these additional genes, the higher expression of four genes (BMP2, RPL18A, RPL19, and RPS12) was also significantly associated with better survival and delayed tumor recurrence in patients with glioma, especially those with grade III glioma." (PMID 38672212, 2024). "However, the RPs (RPL18A, RPL19, and RPS12) showed a more distinct trend, which was statistically significant for both OS and PFS only in grade III gliomas." (PMID 38672212, 2024).
liver cancer (2 papers, 2021 to 2025). An epithelial or non-epithelial malignant neoplasm that arises from the liver. "According to the literature, RPS12 is a tumor marker for liver cancer." (PMID 34350180, 2021). "For instance, analyzing public datasets of cancers such as pancreatic, lung, and liver cancers may reveal the potential of EIF1 and RPS12 as broad-spectrum anti-tumor targets." (PMID 41261408, 2025).
anaplastic carcinoma (1 paper, 2021). "After gene ontology analysis, it was found that plasma cell (RPS12) could potentially contribute to the development of anaplastic carcinoma, while plasma cell (IGHG4) could contribute to Burkitt lymphoma." (PMID 34485161, 2021).
anemia (1 paper, 2023). A reduction in the number of red blood cells, the amount of hemoglobin, and/or the volume of packed red blood cells. "We sought to understand if, similar to other Rp mutant mouse models, Rps12 heterozygous mutants have anemia or defective erythropoiesis." (PMID 37272618, 2023). "Although the Rps12 locus is unusual in Drosophila, in not exhibiting any haploinsufficient phenotype, and in playing a special role during cell competition, Rps12 heterozygous mutant mice resembled mice mutants for other Rp genes in reduced body size, skeletal defects, and anemia." (PMID 37272618, 2023).
Bardet-Biedl syndrome (1 paper, 2021). A ciliopathy with multisystem involvement. "For example, HES2, MAFB, RPS12, RPL12, RPS15, and AFF2 are all associated with cancer, whereas BBS12 is a gene related to Bardet-Biedl Syndrome, a multi-organ genetic disease that can involve hypoplasia of the uterus, ovaries, and fallopian tubes." (PMID 34215221, 2021).
cortical atrophy (1 paper, 2025). "Likewise, in specific cortical areas with less atrophy within neurodegenerative samples, more RPS12 positivity was observed (panel FTLD-TAU), stressing the inverted relationship between RPS12 positivity and degree of cortical atrophy." (PMID 40713859, 2025). "RPS12 positivity decreased with increasing cortical atrophy, irrespective of the neurodegenerative subgroup." (PMID 40713859, 2025).
depression (1 paper, 2024). "In particular, ribosomal protein S19, ribosomal protein S12, ribosomal protein S14, vimentin, and ubiquitin-like modifier activating enzyme 1 mediated the therapeutic effects of EXD on depression and hippocampal damage." (PMID 38915473, 2024).
developmental delay (1 paper, 2019). "If Xrp1 expression causes the developmental delay, and RpS12 is required for elevated Xrp1 expression, then RpS12 should be required for the developmental delay." (PMID 31841522, 2019). "We then re-examined the effect of rpS12 loss of function in developmental delay." (PMID 31841522, 2019).
Pancytopenia (1 paper, 2023). An abnormal reduction in numbers of all blood cell types (red blood cells, white blood cells, and platelets). "Heterozygous loss of Rps12 in the hematopoietic cells impairs translation in the hematopoietic stem and progenitor cells and leads to pancytopenia." (PMID 37272618, 2023). "Post-natal heterozygous deletion of Rps12 in hematopoietic cells using Tal1-Cre-ERT also resulted in pancytopenia with decreased HSC numbers." (PMID 37272618, 2023). "At 14 weeks post Rps12 deletion, we began to observe mild pancytopenia, a significant decrease in bone marrow cellularity, a decrease in HSC numbers, and a trend toward decreased progenitor populations." (PMID 37272618, 2023). "Inducible, conditional heterozygous deletion of Rps12 in adult hematopoietic cells also led to decreased HSC and progenitor cell numbers and pancytopenia." (PMID 37272618, 2023).
pulmonary hypertension (1 paper, 2022). Increased pressure within the pulmonary circulation due to lung or heart disorder. "To further investigate the relationships among the SRP-DGs and risk of SSc-PH, we constructed a nomogram model using seven SRP-DGs (RPL32, RPS12, RPS14, RPS23, RPS3, RPS7, and SRP9) to predict the risk of pulmonary hypertension complications in patients with SSc." (PMID 36518216, 2022).
cancer (13 papers, 2002 to 2025). A tumor composed of atypical neoplastic, often pleomorphic cells that invade other tissues. "The transgene emerged to encode RPS12—a protein of the small ribosomal subunit overexpressed in several cancer types and known to also possess extra-ribosomal functions." (PMID 33273532, 2020). "Mechanistically, EIF1 and RPS12 are central regulators of ribosome biogenesis and translational initiation, processes that are frequently upregulated in cancer cells." (PMID 41261408, 2025). "Overexpression of human RPS12, a subunit of the small ribosomal subunit, whose expression is increased in various cancer types, leads also to a glazed eye phenotype." (PMID 35030229, 2022). "Identification of RPS12 as an unexpected candidate regulator of Wnt secretion in cancer cells is just the first outcome of the large-scale project we initiated to uncover novel cancer-relevant proteins using the Drosophila model." (PMID 33273532, 2020). "Other Rps12 functions that have been suggested in mammalian cells and cancers could now be explored using this conditional knock-out model with tissue-specific Cre-drivers." (PMID 37272618, 2023). "Human Rps12 has also emerged as a candidate regulator of Wnt secretion in cancer cells." (PMID 37272618, 2023). "Despite these findings, the mechanistic understanding of the role of RPS12 in cancer initiation and progression, which might be decoupled from the ribosomal activity of this protein, is lacking." (PMID 33273532, 2020). "This hypothesis is supported by our current results demonstrated that certain genes, such as the ribosomal protein S12 gene, is upregulated in the adjacent tissues of progressive cancers." (PMID 11870519, 2002). "Such cross-cancer investigations can expand the applicability of EIF1 and RPS12 and offer a comprehensive understanding of the general mechanisms of NETs in tumor progression." (PMID 41261408, 2025). "EIF1 and RPS12 emerge as promising candidates for precision medicine, with broader implications for NET-related cancer research." (PMID 41261408, 2025). "For plasma samples [n = 57; 30 controls, 27 cancers (stages II: 13, III: 6, IV: 8)], RPS12 had the lowest standard deviation in controls." (PMID 39146279, 2024). "ROC curve analyses revealed that methylation status of each individual genes could significantly distinguish primary carcinoma from adjacent normal mucosa, as measured by AUC value (DLX6-AS1: 0.941; lnc-DPH5-1: 0.833; lnc-PRSS2-6: 0.913; lnc-RPS12-6: 0.916; lnc-SFRP4-2: 0.830; SOX21-AS1: 0.921)." (PMID 35127488, 2021).
tumor (10 papers, 2016 to 2026). "Importantly, our MR analysis validated the causal relationships between EIF1 and RPS12 and GC development, providing robust genetic evidence for their involvement in tumor biology." (PMID 41261408, 2025). "In contrast, the ‘tumor cells 2’ cluster was characterized by genes associated with protein synthesis (Cmss1, Rpph1, Rps12, Lars2, Ncl2), tumorigenesis (Mt-Rnr2, Hmga2, Mab1b) and cell–cell communication (Gphn, Camk1d, Il31ra, Cmss1, Rpph1), which may be indicative of an inflammatory phenotype." (PMID 39769061, 2024). "In this context, EIF1 and RPS12 may serve as molecular hubs connecting metabolic and translational machinery with immune regulation, ultimately promoting a tumor-permissive microenvironment." (PMID 41261408, 2025). "Upregulation of RTP gene markers (SNCG, CST3 and RPS12) was also found in three resected tumor samples we collected from pPR (pathological partial response) LARC patients after receiving nCRT, which was coherent with the poor regression grade of these patients." (PMID 36658726, 2023).
infection (3 papers, 2022 to 2025). The state of being infected such as from the introduction of a foreign agent such as serum, vaccine, antigenic substance or organism. "COL1A2, RDH13, and RPS12 were down-regulated following infection with the mutant strain, whereas DEGs related to C-type lectins recognition and signaling mechanisms were up-regulated." (PMID 35215144, 2022). "Expression of RPS12 and RPL12 were upregulated after infection with A. veronii, which indicated more protein synthesis in cells." (PMID 37275236, 2023).
RPS12 also shares sentences with these, for which no sentence is quoted: B-cell lymphoma (1 paper); bone marrow failure (1); breast tumors (1); brucellosis (1); Burkitt lymphoma (1); colorectal tumors (1); COVID-19 (1); genetic disease (1); Obesity (1); osteosarcoma (1); Parkinson disease (1); squamous cell carcinoma (1); triple-negative breast carcinoma (1).